SIRT1 (sirtuin 1)
Diseases named in the same sentence as SIRT1 in open-access papers (continued):
Sharing a sentence is not in itself a finding about the gene and the disease.
tumor (continued). "The role of SIRT1 in tumors has long been contentious as it has been shown to act as both a tumor suppressor as well as tumor promoter." (PMID 29717261, 2018). "In fact, dysregulated c-Myc initiates a positive feedback loop between Nampt, the SIRT1 inhibitor DBC1, and SIRT1, that contributes to tumor development and maintenance." (PMID 30631755, 2018). "Resveratrol exert anti-tumor, anti-oxidative, anti-inflammatory, and neuroprotective effects by activating Sirt1." (PMID 30305045, 2018). "The cell proliferation rate measured by the percentage of Ki-67-positive tumor cells were increased in the group implanted with the SIRT1 plasmids and decreased in the group implanted with the miR-30a lentivirus." (PMID 29435152, 2018). "Alternatively, there is much convincing evidence supporting a tumor suppressive role of SIRT1 in carcinogenesis, considering its implication in maintaining genome integrity via chromatin regulation and DNA damage response." (PMID 30380732, 2018). "Overall, we found that in the group of mice subjected to castration and ex527, tumor growth was much slower than in the control groups (p=0.014), and tumor weight was much lower in mice with SIRT1 inhibitor treatment." (PMID 29416748, 2018). "Intriguingly, the statistical analysis showed that SIRT1 significantly colocalizes with H3k4ac over H3k9ac on targeted genes across all tumor subtypes." (PMID 30093977, 2018). "Numerous in vivo and in vitro studies have demonstrated that resveratrol can protect the myocardium and exert anti-tumor, anti-oxidative, anti-inflammatory, and neuroprotective effects by activating Sirt1." (PMID 30305045, 2018). "They reported that SIRT1 inhibits tumor growth in vivo by suppressing the expression of survivin, a member of the inhibitor of apoptosis (IAP) family that drives cell proliferation and viability." (PMID 30380732, 2018). "To elucidate the mechanism for the therapeutic efficacy of Comp 5 in vivo, we examined the immunoreactivity of SIRT1 and p62 in tumor tissues of U87MG xenograft mice." (PMID 29991742, 2018). "SIRT1 also functions in the regulation of metabolism and maintaining the integrity of the genome, and thus has been described as a potential tumor suppressor." (PMID 29636061, 2018). "Notwithstanding, a single retrospective study incorporating 822 BC patients found SIRT1 expression to correlate with tumor aggressiveness and reduced disease-free-survival (DFS)." (PMID 30319540, 2018). "Taken as a whole, this study describes a new regulatory axis that miR-30a possesses tumor suppressor activity by negatively regulating SIRT1 expression in lung tumorigenesis." (PMID 29435152, 2018). "Surgical castration was performed when the tumor volume reached 200 mm3, followed by treatment with the SIRT1 inhibitor ex527, and further growth of the tumors was monitored." (PMID 29416748, 2018). "In the purified cells from the separated tumor tissues, we found that the expression level of SIRT1 in LV-miR-29b groups was obviously lower than that in the LV-ctrl groups." (PMID 29552311, 2018). "Consistently, lncRNA-PRLB and SIRT1 expression were lower, while miR-4766-5p expression was higher in tumor tissues derived from the shPRLB group than those from controls." (PMID 29752439, 2018). "Some evidences, in fact, support a Sirt1 role as tumor suppressor while others suggest for an oncogenic potential." (PMID 30304806, 2018).
tumor (continued). "In summary, we have demonstrated that SIRT1 acts as a tumor suppressor in terms of invasion and metastasis of GC." (PMID 30250020, 2018). "It has been reported that the relationship of SIRT1 expression and tumor metastasis in several kinds of tumors." (PMID 28112277, 2017). "In an in vitro assay, we found that the anti-tumor mechanism of SB was due to P38/SIRT1-regulated cell apoptosis through G2/M phase arrest and ER stress-, intrinsic mitochondrial-, and extrinsic FAS/FASL-mediated pathways." (PMID 29312612, 2017). "Further, we also found in alginate tumor microenvironment cultures of CRC cells that resveratrol-induced up-regulation of Sirt1, blocked CRC cell proliferation and concomitantly suppressed Integrin and activation of FAK." (PMID 28953264, 2017). "In conclusion, our findings are the first to focus on the role of SIRT1 on tumor-like invasion of the synovia and cartilage destruction in RA pathogenesis." (PMID 29179491, 2017). "As a Sirt1 inhibitor, sirtinol has displayed anti-tumor and anti-inflammatory properties, but its impact on allograft rejection and its molecular mechanisms of action have not yet been reported." (PMID 29090089, 2017). "Genetically manipulated MSCs overexpressing sirtuin 1 have been shown to decrease tumor size in a subcutaneous tumor mouse model partly through the recruitment of NK cells." (PMID 29181035, 2017). "Recently, it was reported that transgenic SIRT1 expression promoted carcinogenesis in PTEN-deficient mice, whereas enterocyte-specific inactivation of SIRT1 reduced the tumor load in APC+/min mice." (PMID 28977971, 2017). "Recent studies have demonstrated that compared with normal liver or surrounding tumor tissues, SIRT1 is strongly overexpressed in human HCC." (PMID 28881735, 2017). "SIRT1 plays an important role in regulating several biological functions, such as metabolism, aging, DNA damage and tumor development." (PMID 28112277, 2017). "SIRT1 protein is a positive regulator of EMT and tumor metastasis; higher SIRT1 expression relates to tumor progression, and lower SIRT1 expression relates to tumor regression." (PMID 27935857, 2017). "As we observed significant upregulation of miR-204 in tumor cells transduced with miR-204-lentivirus (miR-204-LV), the protein level of SIRT1 was obviously decreased in them." (PMID 29228612, 2017). "SIRT1 expression and function are found to vary drastically depending on cell and tumor types, making it a multifaceted enzyme with contradictory functions depending on its upstream regulators and downstream targets." (PMID 29340027, 2017). "According to previous reports, SIRT1 plays a role as a tumor promoter in endometrial cancer by targeting sterol regulatory element binding protein 1 (SREBP1) and lipogenesis." (PMID 28754906, 2017). "As research advanced, SIRT1 is also found to play a role in tumor suppression by promoting genetic stability and apoptosis through interacting with certain proteins." (PMID 27659520, 2017). "These in vivo studies further verified that administration of cryptolepine inhibits tumor growth by modulating AMPKα1/2/mTOR, and reducing the c-Myc/SIRT1/PGC-1α signaling cascade involved in mitochondrial dynamics and biogenesis." (PMID 28473727, 2017).
tumor (continued). "Although SIRT1 has been suggested to play a tumor-suppressive role, there has been convincing evidence arguing for its oncogenic properties." (PMID 28977971, 2017). "Sirt1 has been emerged as a crucial regulator in many physiological processes, such as aging, differentiation, apoptosis, DNA damage and tumor development in mammalians." (PMID 28882183, 2017). "Result showed that acetylation of K-Ras was decreased by long-term resveratrol feeding, suggesting that resveratrol blocked K-Ras/PI3K/AKT pathway through deacetylase SIRT1 in spontaneous neoplasms." (PMID 28903430, 2017). "It confirmed that SIRT1 served as a tumor suppressor and resveratrol improved its expression apparently in spontaneous neoplasms of the fish." (PMID 28903430, 2017). "Dramatically, the tumor showed an increased weight and volume when rabbit anti-murine CXCL10 was additionally injected in tumor-bearing mice with MSCs-Sirt1 and 4T1 cells coinjection, compared with those under rabbit-serum injection." (PMID 27782173, 2016). "This involves the acquisition of stem cell features and metabolic reprogramming with a shift from glycolysis to oxidative phosphorylation and is notably dependent on PCG1a, a protein well known for its regulation by SIRT1, and important in tumor growth." (PMID 27494892, 2016). "Taken together, these results indicate that the resveratrol/Sirt1 signaling pathway induces an MET (mesenchymal to epithelial transition) phenotype in CRC cells in the alginate tumor microenvironment." (PMID 26959057, 2016). "Both in vivo and in vitro data demonstrated that SIRT1 overexpression increases uncontrolled tumor growth in HCC." (PMID 26824501, 2016). "In agreement, NAD+-dependent deacetylase SIRT1 displayed a higher expression and activity in tumor tissues." (PMID 27566573, 2016). "SIRT1 expression in GC varies according to tumor type, the tumor microenvironment, and cellular stress, and the role of SIRT1 in GC progression is still not fully understood." (PMID 28070138, 2016). "Knockdown of SIRT1 by short hairpin RNA (shRNA) accelerates tumour xenograft formation in HCT116 cells, whereas SIRT1 overexpression inhibits tumour formation." (PMID 27793039, 2016). "To further determine the function of SIRT1 in tumor metastasis in vivo, we constructed stably transfected MHCC97H-sh-control-luciferase and MHCC97H-sh-SIRT1-luciferase cells." (PMID 27081083, 2016). "On the other hand, a collection of in vivo mouse models provided evidence that SIRT1 maintains genetic stability in normal cells and decelerates tumor formation." (PMID 27916001, 2016). "Overexpression of SIRT1 has been detected in both gastric and gastroesophageal junction cancers and has been related to tumor stage and occurrence of lymph node metastases." (PMID 27379175, 2016). "The apparent opposite role of SIRT1 seems contradictory at first, but the seemingly multifaceted functions of SIRT1 make this possible; it seems that the role of SIRT1 as a tumor suppressor or promoter is highly context-specific." (PMID 27542221, 2016). "Together, these studies indicate complex, and possibly tissue-dependent roles of SIRT1 in both tumor promotion and suppression." (PMID 27708228, 2016). "Our data demonstrate a role of the AKT1/SIRT1/FOXM1 axis in the expression of the tumor suppressor ERβ." (PMID 26885609, 2016). "In conclusion, we found that resveratrol, by targeting the subcellular Sirt1 signaling pathway, is one of the main mechanisms of the anti-tumor effects of resveratrol on CRC cells." (PMID 26959057, 2016).
tumor (continued). "Then we made a depletion on NK cells in mice and the result showed that the antitumor effect of MSCs-Sirt1 was obviously weakened in vivo, which indicated that NK cells played an important role in tumor inhibition induced by MSCs-Sirt1 in tumor-bearing mice." (PMID 27782173, 2016). "Dramatically higher numbers of IFN-γ-secreting NK cells were detected in tumor xenograft tissues of MSCs-Sirt1 group than those in tumor xenograft tissues of control group, as well as MSCs-GFP group." (PMID 27782173, 2016). "For example, it has been reported that Beclin-1 is acetylated by p300 and deacetylated by SIRT1 at lysine residues 430 and 437 which further influences the autophagosome maturation and tumor growth." (PMID 28070138, 2016). "To further investigate the effect of SIRT1 on HCC proliferation in vivo, we subcutaneously injected mice with MHCC97H-sh-SIRT1 cells and dynamically monitored tumor growth (Figure 2E1)." (PMID 27081083, 2016). "SIRT1 overexpression was frequently detected in human HCC specimens and was associated with microvascular invasion (P = 0.0039), advanced tumor node metastasis (TNM) stages (P = 0.0016), HCC recurrence (P = 0.021) and poor outcomes (P = 0.039)." (PMID 27081083, 2016). "On the contrary, in vivo SIRT1 inhibition promoted xenograft tumor growth, thus suggesting possible off-target effects on the tumor microenvironment and adding another layer of complexity to the characterization of the EMT-related activity of sirtuins." (PMID 27379175, 2016). "In contrast, several reports have described SIRT1 as a tumor suppressor that safeguards the organism from oncogenic stress." (PMID 27528025, 2016). "The number of activated macrophages was increased in RM-1 and PC2 tumor tissues of MSCs-Sirt1 group, compared to other groups." (PMID 27764779, 2016). "The data indicate that the effect of MSCs-Sirt1 in tumor suppression can be greatly blocked by CXCL10 inhibition." (PMID 27782173, 2016). "To explore the role of SIRT1 in tumor-stroma interplay, we designed an in vivo tumor model using SIRT1-transgenic mice." (PMID 26992208, 2016). "Such suggestion is based on the reported positive relation between SIRT1 expression and tumor proliferation." (PMID 26999517, 2016). "Correlation of tumor grade with SIRT1 level was evident in the present study by significantly higher SIRT1 levels in grade 2 than in grade 1 and in grade 3 than in grade 2." (PMID 26999517, 2016). "Comparing tumor growth between WT and TG mice, control and SIRT1-overexpressing tumors both grew more quickly in TG mice." (PMID 26992208, 2016). "B16F10 tumors excised from mice were weighed (right), which verifies the tumor growth retardation in co-graft with SIRT1 knock-down MEFs." (PMID 26992208, 2016). "A previous study also suggested that SIRT1 expression levels are positively correlated with tumor grade, and patients with higher HCC stages tend to have higher SIRT1 expression." (PMID 26824501, 2016). "More importantly, the de-novo NAD+ synthesis pathway and SIRT1 activity were found significantly enhanced in the tumor tissues of human NSCLC." (PMID 27566573, 2016). "Experiments with a mouse model revealed that overexpression of SIRT1 enhanced HCC tumour metastasis in vivo and also significantly enhanced the invasive and metastatic potential of HCC cells by inducing the epithelial-mesenchymal transition (EMT)." (PMID 27793039, 2016). "In mammalian cells, Sirt1 regulates several biological functions, such as aging, metabolism, DNA damage, and tumor development." (PMID 27764779, 2016). "Conversely, there was an apparent rise of the percentage of TUNEL-positive tumor cells and a significant decline of Ki67-positive tumor cells in MSCs-Sirt1 treatment groups." (PMID 27782173, 2016).
tumor (continued). "Our study, demonstrates that miR-449a acts as a tumor suppressor by inhibiting SIRT1expression, thereby triggering pathways downstream of SIRT1." (PMID 26988912, 2016). "We have also detected large numbers of IFN-γ-secreting NK cells in tumor tissues in the MSCs-Sirt1 group." (PMID 27764779, 2016). "Overall, the role of SIRT1 as either a tumor promoter or a tumor suppressor is still under investigation, and more intense research is needed in order to understand the complex role of SIRT1 in tumorigenesis." (PMID 26999517, 2016). "To analyze the mechanism by which MSCs-Sirt1 recruit NK cells for tumor inhibition, we measured the serum levels of chemokines CXCL9, CXCL10, and CXCL11." (PMID 27764779, 2016). "Having identified that miR-199b controlled CRC invasiveness through SIRT1, we tried to continue investigating its downstream signaling pathways using the Human Tumor Metastasis PCR Array." (PMID 27145368, 2016). "In agreement with our suggestion, many recent reports have shown that SIRT1 has a tumor promoting role." (PMID 26999517, 2016). "The correlation between Nanog expression and MEK1/SIRT1 in tumor tissues was significantly observed in 148 HCC patients (Pearson Correction = 0.013/0.038)." (PMID 26967560, 2016). "Similar tumor growth kinetics and weights were observed in SIRT1 shRNA-expressing MHCC97H tumors and control shRNA-expressing MHCC97H tumors (Figure 2E2, 2E3)." (PMID 27081083, 2016). "It would be interesting to examine the effects of other more potent SIRT1 inhibitors in the KSHV-induced tumor model and explore their therapeutic potentials for KSHV-induced malignancies." (PMID 27708228, 2016). "The bifurcated role of the resveratrol/Sirt1 signaling pathway with various signaling targets in tumor cellular processes suggests the therapeutic potential of resveratrol in the prevention/treatment of human CRC." (PMID 26959057, 2016). "In the current study, we detected high level of IFN-γ-secreting NK cells in tumor tissues excised from mice under MSCs-Sirt1 and 4T1 cells coinjection, compared with those under MSCs-GFP and 4T1 cells coinjection, as well as 4T1 cells injection alone." (PMID 27782173, 2016). "Dramatically higher numbers of IFN-γ-secreting NK cells were detected in both RM-1 and PC2 tumor tissues of MSCs-Sirt1 groups compared to other groups." (PMID 27764779, 2016). "In tumorigenesis, SIRT1 seems to play a contradictory role, acting as both a tumor promoter and tumor suppressor (by inhibiting oncogenes and oncoproteins, similar to survivin)." (PMID 27226812, 2016). "Depletion of CXCL10 dramatically decreased the number of tumor-infiltrating NK cells in tumor tissues of MSCs-Sirt1 treated mice." (PMID 27764779, 2016). "Neutralization of IFN-γ impaired the antitumor effect of MSCs-Sirt1, and the tumor growth was restored." (PMID 27764779, 2016). "Both angiogenesis and senescence play important roles in tumor progression and are known to be modulated by SIRT1." (PMID 26439987, 2015). "Considering the totality of the previously referenced studies, it is possible that a critical link exists between SIRT1 function, lipid homeostasis and hormone-dependent tumor progression." (PMID 25569080, 2015). "DBC1 is interesting because of its putative role for the inhibition of SIRT1 and has been suggested as tumor suppressor." (PMID 25823848, 2015). "Afterward, we evaluated the influence of SIRT1 on tumor growth in vivo in 45-day-old female nude mice bearing into the intrascapular region the SkBr3 cells." (PMID 26225773, 2015).